EPCAM (epithelial cell adhesion molecule)
Diseases named in the same sentence as EPCAM in open-access papers (continued):
Sharing a sentence is not in itself a finding about the gene and the disease.
colorectal cancer (continued). "For HRT-18 colorectal cancer cell lines, the PGMC-KO-EpCAM-3 knockdown vector emerged as the most effective, as its sgRNA sequences targeted the first and third exons of the EpCAM gene, thus facilitating more efficient knockout or downregulation." (PMID 41357552, 2025). "Edrecolomab is an IgG2A mAb against EpCAM, whereas edrecolomab showed limited efficacy in the phase III studies of colorectal cancer." (PMID 41346572, 2025). "As an illustration, in cases of colorectal cancer, tumor development typically requires the introduction of 200–500 EpCAM-high/CD44+ cells; in contrast, injection of 104 EpCAM-low/CD44− cells cannot induce tumor formation." (PMID 40647400, 2025). "We further analyzed the expression of EpCAM and CLDN3 in several cancers, including ovarian, gastric, and colorectal cancers." (PMID 40057807, 2025). "The epithelial cell-adhesion molecule (EpCAM)-based CellSearch® was the first FDA-approved platform for CTC analysis, providing prognostic information in metastatic breast, prostate, and colorectal cancer." (PMID 39518041, 2024). "Knowing that colorectal cancer tumors contain LGR5-positive CSCs, we analyzed the presence of LGR5+ cells in two colorectal cancer tumors by immunofluorescence (together with CD90 and EpCAM) or by flow cytometry (together with AF)." (PMID 39225547, 2024). "In colorectal cancer (CRC) patients, high EpCAM expression suggests poor outcomes, in line with the known critical involvements of EpICD in CRC cell function." (PMID 39010070, 2024). "An approach of combining CAR-NK cells targeting epithelial cell adhesion molecule (EpCAM) with tyrosine inhibitor, regorafenib was able to boost the efficacy of CAR-NK cells against colorectal cancer." (PMID 38726000, 2024). "Examples of common markers for colorectal cancer (CRC) are the carcinoembryonic antigen (CEA) and the epithelial cell adhesion molecule (EpCAM), while these antigens are also expressed by healthy cells." (PMID 38169746, 2023). "Tri-specific TCEs targeting CD3, epidermal growth factor receptor (EGFR), and epithelial cellular adhesion molecule (EpCAM) were developed to specifically kill EGFR and/or EpCAM-expressing colorectal cancer cells." (PMID 36971134, 2023). "Cell salvage was also simulated by taking advantage of EpCAM-expressing cancer cell lines (CaCo-2 and HCT116 colorectal cancer cell lines), which were inoculated at a known amount (40–50 cells/μL) on whole blood collected from healthy blood donors." (PMID 37373781, 2023). "Zhang and colleagues developed TiO2 nanofibers expressing EpCAM and coated upon a silicon substrate to investigate colorectal cancer diagnosis, where utilised colorectal cell lines (BGC823 and HCT116) are both noted to express EpCAM." (PMID 38202461, 2023). "Anti-EpCAM-CAR-NK-92 cells demonstrated potent antitumor cytotoxicity and cytokine production in EpCAM + colorectal cancer cells." (PMID 36153626, 2022). "Blood samples of 316 colorectal cancer patients were used for CTC detection and subtyping with EpCAM, CK8/18/19, vimentin, and twist as biomarkers." (PMID 35493298, 2022). "However, using the same functionalization strategy, our nanorods could be conjugated with different antibodies for different EV surface markers such as EpCAM, which is overexpressed in many types of cancers or claudin 1,7, and Cadherin-17, which are specific for colorectal cancer." (PMID 36514065, 2022). "One of the established recombinant anti-EpCAM mAbs, recEpMab-37 (mouse IgG1, kappa), reacted with EpCAM-overexpressed Chinese hamster ovary-K1 cells (CHO/EpCAM) or a colorectal carcinoma cell line (Caco-2)." (PMID 35735360, 2022). "EVs isolated from HT29 and SW480 colorectal cancer cell lines express CD81 and display differential levels of EpCAM by Western Blotting as well as by ELEXO." (PMID 34155195, 2021).
colorectal cancer (continued). "On the other hand, they reported a novel regimen, combination therapy with EpCAM-specific CARNK-92 cells and regorafenib, which increased anti-tumor efficacy to treat colorectal cancer in mouse models." (PMID 33752707, 2021). "Colorectal cancers with mismatch repair deficiency (loss of MSI-H or mismatch repair protein expression) in which MLH1 promoter methylation is not observed while not exhibiting mismatch repair genes or pathogenic EPCAM variants that cause Lynch syndrome are referred to as Lynch-like syndrome." (PMID 34185173, 2021). "For this purpose, we used bispecific antibodies engaging CD3-EpCAM or CD137-5T4 (ALG.APV-527) and a colorectal carcinoma cell line HCT116 that coexpresses 5T4 and EpCAM on its surface." (PMID 34911975, 2021). "TAAs identified in colon and colorectal cancer include human epidermal growth factor receptor 2 (HER2), CEA, epithelial cell adhesion molecule (EpCAM) and human leukocyte antigen (HLA)." (PMID 32899932, 2020). "Combination therapy of EpCAM-directed CAR NK-92-cells and regorafenib, a potent multikinase inhibitor, resulted in a synergistic antitumor effect using for example colorectal cancer cells or xenograft models." (PMID 32849491, 2020). "Anti-EpCAM mRNA CAR T cells produced anti-cancer activity in murine xenograft models of peritoneal ovarian and colorectal cancers by delaying the progression of tumor growth." (PMID 32899932, 2020). "In this study, we reported a novel regimen, combination therapy with EpCAM-specific CAR-NK-92 cells and regorafenib, to treat colorectal cancer in mouse models." (PMID 30410941, 2018). "FACS was used to assess the surface expression of EpCAM in 293T, 293T-EpCAM, FHC, FHC-EpCAM, and human colorectal cancer cell lines, including HCT116, SW620, and HCT-8." (PMID 30410941, 2018). "Monoclonal antibodies against epithelial cell adhesion molecules (EpCAM, CD326) were introduced in the late 1970’s33, representing the first molecular markers for colorectal cancer." (PMID 27431859, 2016). "Diffuse strong EPCAM protein expression is typically observed in colorectal carcinoma (CRC)." (PMID 26528695, 2016). "The present study analyzed the expression of the epithelial marker, CD326/EpCAM, and the metastatic cancer cell marker, CD26/DPPIV in CTCs obtained from colorectal cancer patients." (PMID 25624884, 2015). "The expression of EpCAM/CD44 in colorectal cancer was analyzed, and the correlation of EpCAMhigh/CD44+ with the biological behavior of colorectal cancer was explored." (PMID 24765173, 2014). "In colorectal cancer emerging from chronic ulcerative colitis, a subset of cells with an ALDH1+/EpCAM+ phenotype has been described to be the cells of origin in the transition from a chronic ulcerative colitis to an overt colorectal cancer." (PMID 24727741, 2014). "Median size of EpCAM+CK+DNA+CD45− CTC found by the CellSearch system in metastatic breast is 13.1 μm, prostate 10.7 μm and colorectal cancer is 11.0 μm." (PMID 23626725, 2013). "A tissue microarray of 1420 primary colorectal cancers and 57 normal mucosa samples was immunostained for CD133, CD166, CD44s, EpCAM, and ALDH1 in addition to 101 corresponding whole tissue sections." (PMID 20606680, 2010). "Cancer stem cells derived from colorectal cancer have been reported to co-express several surface markers, in particular CD166, CD44s, and EpCAM molecules." (PMID 20606680, 2010). "The aim of this study was to elucidate the prognostic impact of putative cancer stem cell markers CD133, CD166, CD44s, EpCAM, and aldehyde dehydrogenase-1 (ALDH1) in colorectal cancer." (PMID 20606680, 2010). "Using both EpCAM antibodies (mAb BerEP4 and mAb KS1/4) for immunomagnetic enrichment in blood samples of 39 patients with colorectal cancer we found heterogenous results in each patient with regard to tumor cell detection." (PMID 20426872, 2010).
colorectal cancer (continued). "EpCAM is widely expressed in epithelial tumors, including pancreatic cancer, and is used as a tumor target in clinical trials of CAR-T cell therapy for gastric and colorectal cancers." (PMID 41417221, 2025). "First, we tested the molecular profiling capabilities of the approach using EVs derived from human breast and colorectal cancer cell lines and from plasma of colorectal cancer patients to recognize the tetraspanin protein CD63 and the epithelial cell adhesion molecule (EpCAM)." (PMID 41373484, 2025). "Therapeutic targets for colorectal cancer have been identified, including CEA and EpCAM." (PMID 38694508, 2024). "The AI model failed to predict two genes, EPCAM (in a patient with colorectal cancer) and VHL (in a patient with acute lymphocytic leukemia (ALL) and Ewing sarcoma)." (PMID 38021917, 2023). "Using a colorectal cancer organoid model, the researchers demonstrated efficient targeting of CAR-NK cells against the ubiquitous epithelial antigen epithelial cell adhesion molecule (EpCAM)." (PMID 37537666, 2023). "Moreover, metformin was also able to inhibit the expression of different markers of stemness in HCT116 colorectal cancer cells, such as aldehyde dehydrogenase 1 (ALDH1), epithelial cell adhesion molecule (EpCAM), Nanog and CD44." (PMID 37681914, 2023). "Briefly, Rg3 repressed the cancer stemness in both colorectal cancer (LoVo, SW620, HCT116) and liver cancer cells (HepG2, MHCC-97L) via reductions in CD24, CD44, and the epithelial cell adhesion molecule (EpCAM) and activation of ARHGAP9, a tumor suppressor gene." (PMID 36012338, 2022). "The assembly of the IS by a trispecific T cell engager (TriTE) against EGFR, EpCAM, and CD3ε in comparison with two bispecific EGFRxCD3ε and EpCAMxCD3ε LiTEs has been also evaluated under the microscope by co-culturing Jurkat cells with colorectal cancer cells expressing EGFR and EpCAM." (PMID 36678761, 2022). "Moreover, the gene expression of other CSC surface markers such as CD44, EpCaM, and CD34 was also found to be regulated by promoter DNA hypermethylation in colorectal cancer." (PMID 36498950, 2022). "EpCAM is proposed as a marker for detecting CTCs, given that it is rarely expressed on the surface of leukocytes but highly expressed in the majority of epithelium-derived cancers, such as BC, HCC and colorectal cancer." (PMID 36369033, 2022). "Several early experiences with CAR T cell therapy in colorectal cancer include phase I trials investigating targets such as transmembrane 4 L six family member 1 (TM4SF1) and epithelial cell adhesion molecule (EpCAM), which are both highly expressed in many epithelial‐derived solid tumors." (PMID 35844304, 2022). "A number of CSC markers linked to colorectal cancer (CRC) have been described, including, but not restricted to, epithelial cell adhesion molecule (EpCAM), and leucine-rich repeat-containing G protein-coupled receptor 5 (LGR5)." (PMID 35008827, 2021). "Indeed, EpCAM, CD166 and CD44 were more robust as markers of colorectal carcinoma (CRC) CSCs than CD133 alone." (PMID 34774101, 2021). "In line with this, the number of EpCAM+ MV decreased 10 days after surgery in colorectal cancer patients, although the effect was not seen for EpCAM+/EMMPRIN+ MV." (PMID 32731639, 2020). "The use of epithelial cell adhesion molecule (EPCAM) immunohistochemistry (IHC) is not included in the colorectal cancer (CRC) screening algorithm to detect Lynch syndrome (LS) patients." (PMID 33003511, 2020). "CellSearch® (Veridex, Raritan NJ), the current clinical standard for CTC enumeration in breast, prostate and colorectal cancer, uses immunomagnetic enrichment of epithelial cell adhesion molecule (EpCAM) expressing cells, but is not approved in NSCLC." (PMID 31462312, 2019). "EpCAM was strongly expressed in 293T-EpCAM, FHC-EpCAM, and all three colorectal cancer cell lines but was absent in the 293T and FHC cell lines." (PMID 30410941, 2018).
colorectal cancer (continued). "Taken together, these data indicate that aptamer-siRNA chimera is able to effectively downregulate survivin in EpCAM-positive colorectal cancer cells both in vitro and in vivo in the absence of transfection reagent." (PMID 28724889, 2017). "In addition to CD133 and EpCAM, distinct cell surface markers (including CD44 and CD26) help delineate tumor-initiating CSCs in colorectal cancer tissues." (PMID 23826249, 2013). "In a previous immunohistochemical study on colorectal cancer from the several potential CSC markers (ABCG5, ALDH1, CD24, CD44, CD90, CD133, EpCam) that have been proposed for solid tumors, only ABCG5 expression in tumor budding cell was found to be associated with poor survival of the patients." (PMID 23316479, 2012). "The aim of this study was to elucidate the expression and the prognostic role of CD133, CD166, CD44s, EpCAM, and ALDH1 expression in colorectal cancer, by using a tissue microarray including 1420 primary colorectal cancers with full clinicopathological data and follow-up." (PMID 20606680, 2010). "Therefore, this study employs genetic engineering techniques to construct an EpCAM overexpression vector and a CRISPR/Cas9 knockdown vector, while also establishing colorectal cancer cell lines with EpCAM overexpression as well as downregulated or knocked down EpCAM." (PMID 41357552, 2025). "This study successfully constructed EpCAM-CAR cells and found that they can target and recognise EpCAM-positive tumour cells, secrete killer cytokines TNF-α and IFN-γ and better inhibit the growth and metastasis of colorectal cancer in vitro and in vivo than unmodified T cells." (PMID 39107717, 2024). "To determine whether these CD45+ cells originated from cancer, we sorted three populations of single cells from three colorectal cancer patients by FACS: (a) CD45+ Lineage-APC+ WBCs (Lineage contains CD3/14/16/19/20/56); (b) CD45+ Lineage-APC- EpCAM+ CTCs; (c) CD45− EpCAM+ CTCs." (PMID 38575583, 2024). "For example, in cancer cells, ITGB1 can bind to EpCAM and regulate cell adhesion; The high expression of ITGB1 may be related to the poor prognosis of colorectal cancer and can lead to the migration and invasion of colorectal cancer cells." (PMID 37007126, 2023). "This has not previously been reported for colorectal cancer, but CTCs expressing EpCAM and CD45 were shown to be a poor prognostic marker in lung cancer, suggesting that we might be identifying a potentially aggressive population." (PMID 34945008, 2021). "The CellSearchTM system (Veridex, LLC, Raritan, NJ, USA), depending on epithelial cell adhesion molecule (EpCAM) marker to enrich and isolate CTCs, was the first and only semi-automated CTCs enumeration assay approved by FDA for the diagnosis of metastatic breast, prostate, and colorectal cancers." (PMID 29792200, 2018). "Here we describe the use of an oligonucleotide chimera made up of an EpCAM-specific aptamer and a survivin siRNA to downregulate survivin in both the bulk and colorectal cancer stem cells without the aid of transfection agent or other delivery vehicles such as viral vectors or nanodrug carriers." (PMID 28724889, 2017). "Therefore, we investigated whether the lung and colorectal carcinoma cells used in this study express additional tumour stem cell markers such as CD44 and CD133, as we showed that they expressed EpCAM." (PMID 19002182, 2008). "EpCAM-negative CTC, thus undetected through CellSearch®, have been correlated with poor prognosis in colorectal cancer patients in the course of antiangiogenic treatment as well as with the emergence of brain metastasis in triple-negative breast cancers." (PMID 31636732, 2019).
prostate carcinoma (216 papers, 2006 to 2026). A carcinoma that arises from epithelial cells of the prostate gland. "EpCAM was over-expressed in primary prostate tumors and lymph node metastases and was associated with prostate cancer cell proliferation, invasion and metastasis." (PMID 40017594, 2025). "We evaluated the EpCAM expression of CTCs from 13 metastatic prostate cancer patients undergoing Diagnostic LeukApheresis (DLA)." (PMID 37055551, 2023). "As the number of CTCs in the blood is low, we enriched CTCs through the depletion of leukocytes from diagnostic leukapheresis products of 13 prostate cancer patients and measured EpCAM expression using quantitative flow cytometry." (PMID 37055551, 2023). "Downregulation of PI3K/Akt/mTOR signaling pathway proteins occurs subsequent to EpCAM silencing and is associated with the decreased colony formation, proliferation, and cellular invasion in prostatic cancer cells." (PMID 35986321, 2022). "In the present study, CK19 and EpCAM were also found to be of diagnostic value for primary prostate cancer." (PMID 35402423, 2022). "Researchers studying this phenomenon found that overexpression of epithelial cell adhesion molecule (EpCAM) in prostate cancer cells is associated with chemoresistance and radioresistance." (PMID 35992826, 2022). "EpCAM-regulated carcinogenesis was proved to be associated with PI3K/Akt/mTOR signaling pathway activation in animal experimentation on prostatic cancer." (PMID 35986321, 2022). "EpCAM, associated with prostate cancer, was upregulated in 22Rv1 (26%) and LNCaP (32%), while PC3 (3%) and PNT1A (1%) showed low levels." (PMID 34079007, 2021). "It has been reported that EpCAM is involved in the response to chemotherapy/radiotherapy in a xenograft model of prostate cancer and that its knockdown causes significant tumor growth inhibition and induction of sensitivity to chemotherapy/radiotherapy." (PMID 33767581, 2021). "Here, we analyzed the expression patterns of two PCSC-associated membrane markers, CD44 and EpCAM, in 3D-cultured prostatospheroids derived from three different prostate cancer cell lines (AR-positive LNCaP and VCaP; AR-negative DU145)." (PMID 32183880, 2020). "Fluorescence imaging revealed the migration of the NK cells to tumor-associated epithelial cell adhesion molecule (EpCAM) expressing human prostate cancer cells in a mouse model 90 min-post intravenous injection of the NK cells." (PMID 32455886, 2020). "The tumour cell isolation efficiency and the mRNA levels of the prostate cancer biomarkers androgen receptor variant 7 (AR-V7) and total AR, as well as epithelial cell adhesion molecule (EpCAM) were measured." (PMID 28498319, 2017). "Studies have shown that EpCAM is expressed on CSCs from prostate cancer and its expression is associated with prostate cancer cell proliferation, tumorigenesis, metastasis, and chemo/radioresistance." (PMID 25636521, 2015). "EpCAM has been reported to be responsible for persistence of minimal residual disease and latent relapse of prostate cancer, presumably by affecting the susceptibility to the EGF ligand and regulating the AMPK signaling pathway." (PMID 25967040, 2015). "Kaplan-Meier curves demonstrated that PCA3, ARV7, and EpCAM were associated in androgen-deprivation therapy (ADT) failure time which is defined as from the initiation of ADT in hormone-sensitive stage to the development of castration-resistant prostate cancer." (PMID 35402423, 2022). "Kaplan-Meier curves depicted the association of PCA3, ARV7, and EpCAM in the time to failure of androgen deprivation therapy (ADT) which is defined as from the start of hormone-sensitive phase of ADT to the development of castration-resistant prostate cancer." (PMID 35402423, 2022).